WASHC2A (WASH complex subunit 2A)
Description:
Acts at least in part as component of the WASH core complex whose assembly at the surface of endosomes inhibits WASH nucleation-promoting factor (NPF) activity in recruiting and activating the Arp2/3 complex to induce actin polymerization and is involved in the fission of tubules that serve as transport intermediates during endosome sorting. Mediates the recruitment of the WASH core complex to endosome membranes via binding to phospholipids and VPS35 of the retromer CSC. Mediates the recruitment of the F-actin-capping protein dimer to the WASH core complex probably promoting localized F-actin polymerization needed for vesicle scission. Via its C-terminus binds various phospholipids, most strongly phosphatidylinositol 4-phosphate (PtdIns- (4)P), phosphatidylinositol 5-phosphate (PtdIns-(5)P) and phosphatidylinositol 3,5-bisphosphate (PtdIns-(3,5)P2). Involved in the endosome-to-plasma membrane trafficking and recycling of SNX27-retromer-dependent cargo proteins, such as GLUT1. Required for the association of DNAJC13, ENTR1, ANKRD50 with retromer CSC subunit VPS35. Required for the endosomal recruitment of CCC complex subunits COMMD1 and CCDC93 as well as the retriever complex subunit VPS35L.
Synonyms: FAM21A; FAM21B; bA56A21.1; bA98I6.1; FLJ10824
Tractability: Antibody: UniProt places it where antibodies can reach, with medium confidence; its Gene Ontology location is reachable by antibodies, with medium confidence. PROTAC: ubiquitination databases record sites on it.
Gene: Protein-coding gene on chromosome 10 (50,067,881 to 50,133,510, forward strand). Ensembl gene ENSG00000099290.
Subcellular location: Early endosome membrane; Cell membrane
Subcellular location (Human Protein Atlas): Vesicles; Cytosol; Nucleoli
Gene Ontology:
Molecular function: protein binding; phosphatidylinositol phosphate binding; retromer complex binding
Biological process: protein localization to endosome; endosomal transport; regulation of Arp2/3 complex-mediated actin nucleation; retrograde transport, endosome to Golgi
Cellular component: early endosome membrane; early endosome; plasma membrane; WASH complex; cytosol
Genetic constraint (gnomAD): Loss-of-function variants: 73 observed, 109.53 expected, observed/expected ratio (o/e) 0.67, 90% interval 0.55 to 0.81. The synonymous counts are far from expectation, so gnomAD's model fits this gene poorly and the ratio says little. Missense variants: 933 observed, 1,246.2 expected, observed/expected ratio (o/e) 0.75, 90% interval 0.71 to 0.79. Synonymous variants: 307 observed, 445.23 expected, observed/expected ratio (o/e) 0.69, 90% interval 0.63 to 0.76.
Homologues: Orthologues: chimpanzee WASHC2A (99% identical), dog WASHC2C (81% identical), mouse Washc2 (74% identical), rat Washc2c (73% identical), Drosophila melanogaster FAM21 (21% identical), zebrafish washc2c (16% identical). Paralogues in human: WASHC2C (99% identical), RCSD1 (7% identical).